IGF1R (insulin like growth factor 1 receptor)
Diseases named in the same sentence as IGF1R in open-access papers (continued):
Sharing a sentence is not in itself a finding about the gene and the disease.
cancer (continued). "Recently added to this list, is the investigation of plasma IGF-1R in cancer patients: anti-IGF-1R antibodies sequestered by circulating IGF-1R in the plasma could diminish any proposed therapeutic effect on cancer cells." (PMID 25964779, 2015). "The IGFs/IGF1R system has been implicated in tumorigenesis, cancer development and progression, while IRR has been suggested to function as an alkali sensor; we will focus here only on interactions among insulin, IGF1, IGF2, IR and IGF1R." (PMID 25680077, 2015). "Therefore, effective regimens to inactivate the IGF-1R pathway have been anticipated to provide clinical benefits to cancer patients." (PMID 26515601, 2015). "We also investigated whether infiltrating stromal cells contribute to cancer metastasis within an IGF-1R blockade." (PMID 26465273, 2015). "Further steps include xenograft models that will provide the rationale to investigate the clinical efficacy of dual PARP and IGF-1R inhibition in cancer cells, an approach that could expand the subset of patients who may benefit from PARP inhibitors." (PMID 26510816, 2015). "IGF-1R is overexpressed in many tumors and is an important target in cancer therapy." (PMID 25127364, 2014). "Therefore, co-targeting IGF-1R and IR for ubiquitination and degradation by well-designed engineered ubiquitin ligase represent an alternative therapeutic strategy for the treatment of cancers co-expressing IGF-1R/IR." (PMID 24970814, 2014). "Therefore, well-designed engineered ubiquitin ligase represents an effective therapeutic strategy for the treatment of the cancers with co-expressed IGF-1R/IR." (PMID 24970814, 2014). "IGF1R is also key in regulating cell growth and proliferation during cancer development." (PMID 24765210, 2014). "Searching for therapies inhibiting only IGF-1R kinase activity may appear to invalidate the IGF-1R as a target for cancer therapy, while many potential drugs that modify alternative downstream effects, the “biasing agonists”, are not considered." (PMID 24276851, 2014). "Together, these results suggested that engineered ubiquitin ligase PTB-U-box, via IGF-1R and IR degradation, could inhibit cancer glucose metabolism through preventing Glut4 membrane translocation." (PMID 24970814, 2014). "Indeed, there is very little to encourage the further use of targeting the IGF-1R as a single agent in treatment of human cancer, except in a few, relatively rare tumors." (PMID 25333772, 2014). "Insulin-like growth factor-1 receptor (IGF-1R) is involved in cancer cell proliferation." (PMID 25289088, 2014). "Within the IGF network not only the IGF1R but also the INSR exerts cancer-promoting functions." (PMID 24809298, 2014). "The complex relationship between altered INSR isoforms and cancer prognosis may help explain the challenges associated with targeting the IGF1R pathway in NSCLC and other cancers." (PMID 24571613, 2014). "Of importance, differences in IGF1R expression patterns exist between different cancer types." (PMID 24904527, 2014). "miR-145 has been reported to target IGF-1R in several cancer studies." (PMID 25628647, 2014). "However, the status of IGF1R gene polymorphisms and their plausible roles in the IGF signaling promoting cancer growth augments the importance of our findings." (PMID 24392142, 2014). "IGF-1R signaling pathway is prevalent in many cancers, including CRC." (PMID 24173770, 2014). "The identification of these 2 novel mechanisms leading to induction of cell death indicates MK-2206 might be a potential clinical candidate for therapeutic targeting of the subset of IGF1R-dependent cancers in CRC." (PMID 24581231, 2014). "IGF-1R and apoptotic pathways play important roles in cancer progression." (PMID 24970012, 2014).
cancer (continued). "This microRNA suppresses endothelial migration by targeting a set of genes in cancer cells that drive endothelial migration, by activating IGF1R, which is a promoter of endothelial migration, and inhibiting the endothelial MERTK receptor, which is a suppressor of endothelial migration." (PMID 25110710, 2014). "This suggests that IGF-1R inhibitors may yet play a role in the anti-cancer armamentarium, if a reliable biomarker of disease sensitivity can be found in order to allow for rational patient selection and optimization of the risk:benefit ratio." (PMID 24458261, 2014). "IGF-1R is upregulated in a great proportion of cancer cells." (PMID 24809702, 2014). "The insulin-like growth factor-1 receptor (IGF-1R) signaling pathway has been suggested as a target for cancer therapy based on studies showing that the (IGF-1R) is important for cancer cell growth and survival, and is often overexpressed in malignant and premalignant tissues." (PMID 25268741, 2014). "All of these findings provide the rationale for co-targeting IGF-1R and IR in cancer treatment." (PMID 24970814, 2014). "Also, miR-99a mutually regulates its own target, IGF1R expression within a reciprocal regulation, suggesting that the possibility of miR-99a for targeting IGF1R in cancer therapy." (PMID 24410957, 2014). "Increased IGF-1R expression has been found in many cancers and displays prognostic values." (PMID 24667580, 2014). "Again, non-cancerous cells responded to changes in IGF1R and INSRs levels conversely to cancer cells: IGF1R/INSRA overexpression caused decreased migration and invasion, while IGF1R/INSR downregulation was associated with enhanced migration and invasion." (PMID 24809298, 2014). "In addition, IGF1R has emerged as one of the most promising molecular targets in cancer treatment with several technologies being employed in its downregulation." (PMID 24392142, 2014). "Taken together, our results suggest that targeting the IGF-1R/Akt pathway with glucosamine may be an effective therapeutic strategy for treating some type of cancer." (PMID 24438088, 2014). "This indicated the possibility of using miRNA to target IGF1R in cancer therapy." (PMID 24410957, 2014). "This highlights the impact of glycosylation of IGF-1R on cancer behaviors and therapies." (PMID 25362349, 2014). "Most cancers express both the insulin receptor and the IGF1R genes." (PMID 25114970, 2014). "Overexpression and activation of IGF1R and elevated IGF ligand levels have been observed in a number of human cancers, and aberrant signaling of the IGF system has also been associated with cancer resistance." (PMID 24392142, 2014). "Both IGF-1 and IGF-2 enhance the proliferation of human cancer cells through IGF-1R and IR-A." (PMID 24171117, 2013). "IGF1R/INSR hybrids have been identified in multiple human cancers." (PMID 23383308, 2013). "These trails may benefit from studies of the mechanisms in drug resistance and identification of biomarkers that can predict cancer responsiveness to IGF-1R targeted therapies." (PMID 24182354, 2013). "The results also support another function of the IGF-1R to protect cancer cells from apoptosis." (PMID 24103397, 2013). "Our findings in NSCLC and similar evidence of a key role for the IR in other cancer types suggests that residual IGF1R and unencumbered IR signalling may have contributed to the lack of benefit of figitumumab in NSCLC trials." (PMID 23826179, 2013). "Our data when combined with similar observations in other cancer cell types suggest that Akt is likely to have a principal role in mediating the proliferative effects of signalling from the IGF1R/IR." (PMID 23826179, 2013). "Moreover IGF-1R signaling is important in the formation, progression and metastatic spread of many cancer types and provides resistance to anti-cancer drugs." (PMID 23675509, 2013).
cancer (continued). "In addition, multiple clinical trials have started to evaluate the safety and efficacy of selected IGF-1R inhibitors, in combination with standard chemotherapeutic regimens or other targeted agents in cancer patients." (PMID 23525758, 2013). "IGF-1R inhibitors remain a promising focus of investigation for pediatric cancer." (PMID 23383402, 2013). "Thus, IGF1R has been shown to be a promising therapeutic target and both pharmacological and biological agents have been developed to inhibit IGF1R for therapeutic applications in cancer." (PMID 24083380, 2013). "As a single agent IGF1R inhibitors have shown limited success against most cancers, combining IGF1R treatment with other targeted therapies may offer an improved therapeutic outcome." (PMID 24244833, 2013). "It has been reported that miR-7 influences cancer cell migration and invasion by targeting IGF-1R." (PMID 24051403, 2013). "Therefore, NLG at N913 appears to be essential for functional membrane-bound IGF1R and results in an increased response to anti-IGF1R antibody in cancer cells." (PMID 22438913, 2012). "Because one of the cancer-associated mutations involved the same residue (ΔS1278), we measured the coimmunoprecipitation of endogenous RACK1 with wild-type and mutant forms of IGF1R in R-minus cells." (PMID 22778948, 2012). "Some cancer cells express higher levels of IR-A and IGF-1R and hence form Hybrid-A receptors." (PMID 22590494, 2012). "Consistent with prior mutational analyses of the IGF1R C-terminus, the cancer-associated mutations did not significantly affect full-length receptor autophosphorylation in cells." (PMID 22778948, 2012). "The effects of dual inhibition of IGF-1R and mTOR have been examined in myeloma and other cancers." (PMID 23085539, 2012). "A number of cancer molecular markers associated with bone metastasis were assessed by immunohistochemical technique, including PTHrP, OPN, c-Src, MMP2, CXCR4, PI3K, BSP, NFκB, IGF-1R, and BMP4." (PMID 22537906, 2012). "Interestingly, we found that figitumumab-sensitive cancer cells all overexpressed IGF1R; basal expression levels of IR were also much higher compared to that in other resistant cells." (PMID 22438913, 2012). "Because previous studies suggested both positive and negative roles of the IGF1R C-terminus in cell signaling, it was not clear what the predicted effects of the cancer-associated mutations would be." (PMID 22778948, 2012). "In agreement with the reports that overexpression of IGF-1R occurs in a variety of human cancer, we identify that IGF-1R protein expression is highest in the EAC, and is correlated with the surgico-pathological stage, histological grade, and depth of myometrial invasion of EAC." (PMID 22720981, 2012). "Attention to IGF1R has been increasing since the end of the 1980s because of growing evidence that IGF1R-mediated signaling is crucial for the development and progression of multiple types of cancer." (PMID 23242155, 2012). "Indeed, overexpression of IGF-1R is common in several cancers, and pre-clinical studies show that downregulation of IGF-IR signals can reverse the neoplastic phenotype and sensitize cells to anticancer treatments." (PMID 22829853, 2012). "Several mechanisms have been reported to lead to IGF1R activation in cancer cells." (PMID 22778948, 2012). "Furthermore, expression of both is upregulated in many cancer cells and tissues suggesting a role in promoting cancer cell growth and survival and explaining the resistance of certain cancer cells to inhibition of growth by anti-IGF-1R antibodies." (PMID 22140443, 2011).
cancer (continued). "Despite overexpression and invasion promoting ability of Lewis(y), and IGF-1R being separately reported in various types of human cancer, a direct association between Lewis(y) and IGF-1R has never been described." (PMID 22072919, 2011). "Moreover, IGF1R plays an important role in the transformation, motility and metastasis of cancer cells, thus offering an attractive target in cancer therapy." (PMID 21611203, 2011). "This topic merits further investigation because preclinical studies have shown that several cancers expressing high levels of IGF-2 due to IGF-2R mutation and loss of heterozygosity (LOH) are more responsive to both anti-IGF-1R antibodies and anti-sense directed against IGF-2 or IGF-1R." (PMID 22022506, 2011). "Depending on the mechanism, inhibition of IGF-1R may target not only IGF-1R itself but also the hybrid receptors (especially those containing the fetal isoform insulin receptor-A) which favour cancer cell proliferation and are activated by both IGFs." (PMID 21647361, 2011). "Furthermore, IGFs acting via the IGF-1R play a major role in promoting cancer cell growth and survival." (PMID 22140443, 2011). "In addition, many cancer cells express insulin receptors (IRs) and show hyperactivation of the IGF1R-IR pathway." (PMID 22029671, 2011). "Recent studies have shown that Cox-2 mRNA and protein expression in several cancer cell lines are regulated by the insulin-like growth factor (IGF)-1R/PI3K and nuclear factor-kappa B/nuclear factor of kappa light polypeptide gene enhancer in B-cells inhibitor pathways." (PMID 21813027, 2011). "PTK6 may promote human cancer growth by modulating signaling via growth factors receptors, such as IGF-1R and ErbB2." (PMID 20668531, 2010). "These early studies justify the investigation of IGF1R as a target for cancer therapy." (PMID 20924377, 2010). "Taken together, the data reported thus far suggest that IGF1R is an interesting target in cancer." (PMID 20924377, 2010). "In current clinical trials, the main IGF/INS target for cancer therapy is IGF1R." (PMID 20924377, 2010). "Overexpression and activation of IGF1R has been reported in many types of cancer." (PMID 19491901, 2009). "The approach of inhibiting IGF1R with a small molecule is validated by the numerous receptor tyrosine kinases (RTKs) that have been effectively targeted in the treatment of cancer, including Bcr-Abl (imatinib), EGFR (erlotinib, gefitinib) and EGFR/ErbB2 (lapatinib)." (PMID 19732452, 2009). "The insulin-like growth factor 1 receptor (IGF-1R) plays numerous crucial roles in cancer biology." (PMID 17406664, 2007). "Targeting of IGF-1R is more and more seen as a promising option for future cancer therapy." (PMID 15956962, 2005). "In addition, IGF-2, whose expression normally is strictly controlled by parental imprinting is upregulated and functions as an important stimulant of the IGF-1R in cancer." (PMID 15956962, 2005). "Although a huge number of experimental and preclinical investigations have provided encouraging results, clinical trials must be performed and completed to definitely evaluate the usefulness and risks of targeting IGF-1R as an option in cancer treatment of humans." (PMID 15956962, 2005). "Developing effective inhibitors that simultaneously target HIF and IGF1R, along with implementing combination therapies, may significantly improve the prognosis of patients with this aggressive cancer, providing new strategies and targets for comprehensive GBM treatment." (PMID 40290443, 2025).
cancer (continued). "Despite modest clinical outcomes from prior trials of IGF1R inhibitors in other cancers, the robust association between IGF1R expression and patient survival in CCA suggests that selecting patients based on IGF1R status could effectively enrich for therapeutic responders." (PMID 41275311, 2025). "In addition to the expression of IGF1R in cancer cells, IGF1R is expressed in immune cells; although, the exact function of IGFs on host immunity and immune cells such as DC remains unclear." (PMID 39450263, 2024). "However, this inhibition was not reversed via ectopic expression of IGF1R in PRKCSH-deficient cancer cells." (PMID 38200153, 2024). "Therefore, we next asked how cell adhesion molecules influence IGF-1R activity in cancer." (PMID 39608716, 2024). "Moreover, activated INSR/IGF1R and JAK kinases in Phos3 could be associated with EMT and cancer stemness, as well as the immunosuppression." (PMID 38650175, 2024). "Therefore, the action of IGF-1 might be minimally affected by IGFBP but rather influenced by the activation of IGF-1R and its downstream signaling pathways to impact cancer progression." (PMID 39290325, 2024). "We propose that intracellular IGF-1R may serve as a putative biomarker for aggressive cancers, and that therapeutic approaches targeting both ITGB1 and IGF-1R may increase IGF-1R cell surface presence to enhance therapeutic efficacy of cell surface-targeted anti-IGF-1R monoclonal antibodies." (PMID 39608716, 2024). "Therefore, IGF-1R has been identified as a promising target for cancer treatment." (PMID 38540176, 2024). "Furthermore, loss of ITGB1 stabilizes IGF-1R protein levels, which may indicate that ITGB1 is required for IGF-1R protein turnover in migratory cancer cells." (PMID 39608716, 2024). "Indeed, ITGAV contributes to IGF1R-mediated EMP in epithelial plastic cancer cells." (PMID 39075581, 2024). "Furthermore, the IGF-1R inhibitor significantly alleviated pain behaviors suggesting that IGF-1R inhibition could reverse cancer pain in rats." (PMID 37242543, 2023). "It was shown that IGF-1 secreted by irradiated CAFs’ binding to IGF-1R on CRC cells activated the AKT/mTOR pathway, causing glucose uptake and lactate release increasing solute carrier family 7 membrane 11 (SLC7A11) expression and promoting glutamine uptake by cancer cells." (PMID 36835075, 2023). "Notably, IR-A is often preferentially overexpressed in advanced cancer compared to IGF1R." (PMID 36672737, 2023). "IGF1R encoding the insulin-like growth factor 1 receptor (IGFR1) is not only implicated in numerous cellular bio-functional processes, i.e., growth, proliferation, differentiation, and apoptosis, but also it plays a critical role in cancer development, progression, and metastasis." (PMID 37719021, 2023). "IGF-1R and its ligands may contribute to human cancer progression." (PMID 36768298, 2023). "Moreover, our data further suggest that this antiviral could be effective for the treatment of those cancers, which remain addicted to the IGF1‐R/AKT/FOXA1 pathway." (PMID 36056637, 2022). "Furthermore, several studies showed that the elimination of cancer stemness by inhibiting IGF-1R signaling could be a considered way of targeting IGF/IGF-1R in cancer therapy." (PMID 36233084, 2022). "Thus, targeting the IGF1R/PI3K/AKT pathway may be a therapeutic strategy to fight this lethal cancer based on mechanistic evidence." (PMID 36358827, 2022). "Decorin could also target insulin-like growth factor 1 receptor (IGF1R) on the surface of cancer cells and inhibit its downstream signaling or target vascular endothelial growth factor receptor 2 (VEGFR2) on the surface of endothelial cells to promote autophagy." (PMID 36033387, 2022).